STAT3 (signal transducer and activator of transcription 3)
Diseases named in the same sentence as STAT3 in open-access papers (continued):
Sharing a sentence is not in itself a finding about the gene and the disease.
cancer (continued). "Accumulating studies reported the important role of microRNAs (miRNAs) in the regulation of gene expression, among of which, the miR-124/STAT3 interaction has been widely reported in various cancers, while its role in EC has not been investigated yet." (PMID 25928665, 2015). "Both HIF-1α and Stat3 promote aerobic glycolysis and downregulate oxidative phosphorylation in cancer cells, suggesting that GRIM-19 may downregulate aerobic glycolysis by reducing HIF-1α and Stat3 levels and activities." (PMID 25575809, 2015). "To investigate whether MEK inhibitors activate JAK2/STAT3 signal pathways, we examined the effects of MEK inhibitors in K-Ras mutant cancer cell lines." (PMID 25961376, 2015). "NF-κB and STAT3 are activated in the majority of inflammatory-based diseases and in cancer, where they are acting as non-classical oncogenes." (PMID 26501341, 2015). "In this review, we describe our recent studies on the induction of miR-21 by type I IFN, the role of the STAT3 and NFκB signaling pathways in IFN-induced miR-21 expression, the role of miR-21 in different cancers and the role of miR-21 in regulating the antiviral response." (PMID 26610525, 2015). "Honokiol targets multiple signaling pathways such as nuclear factor κB (NF-κB), signal transducers and activator of transcription 3 (STAT3), mammalian target of rapamycin (mTOR) and epidermal growth factor receptor (EGFR), which have great relevance during cancer initiation and progression." (PMID 25846316, 2015). "Cancer induced hepatic expression of ER-stress markers BiP (binding immunoglobulin protein), IRE-1α (endoplasmic reticulum to nucleus signaling 1), and inflammatory intermediate STAT-3 (signal transducer and activator of transcription 3)." (PMID 25789991, 2015). "Nonetheless, the present data warrant assessment of the survival benefits of curcumin analogs in humans, particularly because no inhibitors of β-catenin or STAT3 have been approved for clinical use as chemotherapeutic agents for cancer." (PMID 25331984, 2015). "In this review, we describe our recent studies on the induction of miR-21 expression by type I IFN, the role of the STAT3 and NFκB signaling pathways in IFN-induced miR-21 expression, the role of miR-21 in different cancers and the role of miR-21 in regulating the antiviral response." (PMID 26610525, 2015). "In human cancer cells, these dual inhibitors block the auto-phosphorylation of Aurora A (Thr-288) and the phosphorylation of the Aurora B substrate histone H3 (Ser-10) and the JAK2 substrate STAT3 (Tyr-705)." (PMID 24930769, 2014). "However, in cancer cells, including breast, ovarian and prostate, the JAK2/STAT3 pathway is constitutively active in the majority of cases." (PMID 24886434, 2014). "Furthermore, treatment of cancer cells with EGFR inhibitors such as afatinib and dacomitinib can activate the IL-6/JAK/STAT3 signaling pathway, which in turn induces resistance to these agents." (PMID 24662938, 2014). "Signal transducer and activator of transcription 3 (STAT3) is a well-known transcription factor and regulates a variety of cellular processes, including cell proliferation and survival, oncogenesis and cancer metastasis in GC." (PMID 24527098, 2014). "There were also gene sets related to cancer signaling pathways (MYC, STAT3, and CDH1) or genes moderately involved in cancer (IRF4, SOX4, and EZH2), as well as some associated with various aspects of cancer such as cell transformation, metastasis, and response to therapeutics." (PMID 25122487, 2014). "Although STAT3 activity has been shown to influence SKP2 expression and subsequently p27 levels in several cancer cells, it had remained whether STAT3-mediated SKP2/p27 regulation exhibited an important role in the direction of senescence program." (PMID 25412315, 2014). "According to previous reports, p-STAT3 could interact with p-c-Jun to regulate MMP-1, MMP-7 or other genes expression in human cancers." (PMID 25070240, 2014).
cancer (continued). "As a downstream effector of IL-6, STAT3 can activate transcription of miR-21 and miR-181b-1 which directly target PTEN and cylindromatosis (CYLD) tumor suppressor genes linking inflammation to cancer." (PMID 25126546, 2014). "Widely studied anti-cancer activity; reported to target EGFR, STAT-3, Akt, and NF-κB pathways." (PMID 24833337, 2014). "Not surprisingly, aberrant expression of STAT3 has been documented in the majority of advanced malignancies and cancer cells in culture." (PMID 24806510, 2014). "In other tissues and cancer types, the senescence response engaged by persistent JAK/STAT3 signaling may be more difficult to hijack." (PMID 24675570, 2014). "Cancer progression could be induced by the activation of PI3K, MAPK, and STAT3 pathways, respectively." (PMID 24787299, 2014). "Previous studies also reported that STAT3 was the key factor in the mechanism of sorafenib resistance, and STAT3 rather than Raf-1 was critical in the anti-cancer effect of sorafenib." (PMID 24418169, 2014). "Despite its importance to normal physiology and pathophysiology, however, little is known about how Stat3 achieves its native state within the cell, information that potentially could be exploited to develop novel therapies for AD-HIES and/or cancer." (PMID 24756126, 2014). "IL-6 is pro-inflammatory, promotes steatohepatitis and activates signal transducer and activator of transcription 3 (STAT3) in hepatocytes, and all three mechanisms may be related to cancer induction." (PMID 25533006, 2014). "Moreover, an autocrine signaling loop involving IL-6, STAT3, and AhR was found to sustain the constitutive expression of IDO1 in human cancer cells." (PMID 25360135, 2014). "PTEN is also an example of same direction of effect in LCLs and cancer cells, however unlike STAT3, increased levels of PTEN convey sensitivity." (PMID 24699359, 2014). "Although their exact mechanism of STAT3 inhibition is not clear, two other compounds are actually tested in early phase clinical trials for cancer patients." (PMID 25268165, 2014). "In addition, the constitutively activated STAT3 protein, and the expression of STAT3-regulated antiapoptotic (Bcl-xL), proliferative (c-Myc), and angiogenic (VEGF) proteins were also down-regulated in response to AL in human SW620 cancer cells." (PMID 23848964, 2013). "The low toxicity of berberine and its effective inhibition of STAT3 and tumorigenic growth of NPC make it a potential anti-cancer drug or even chemopreventive agent for NPC through its inhibitory effects on inflammation which is common in premalignant and cancerous NPC tissues." (PMID 24380387, 2013). "Abnormal cell cycle regulation due to Cyclin D1 overexpression is a common occurrence in human cancers (including NPC), and both EGFR and STAT3 could target cyclin D1 promoter activity." (PMID 24499623, 2013). "The role of STAT1 and STAT3 pathways in the production of CXCL5 in cancer has not been well studied." (PMID 24274066, 2013). "Given the importance of STAT3 and inflammation in NPC pathogenesis, we set out to examine whether berberine could suppress activation of STAT signaling to exhibit anti-cancer effects using in vitro and in vivo models." (PMID 24380387, 2013). "We reasoned that once STAT3 up-regulated hTERT, hTERT then started to function as an activator for CD44 in the integrated fashion which triggers the pSTAT3 signaling again, resulting in the cancer stem cell traits." (PMID 24386318, 2013). "Most of the previous studies have reported that STAT3 activation in aggressive malignancies and other carcinomas is a negative prognostic factor." (PMID 24116074, 2013).
cancer (continued). "Constructive expression of STAT3 can up-regulate the expression of MMP-2 and MMP-9, which are able to efficiently degrade the extracellular matrix and basement membrane, promoting invasion and metastasis of cancer cells." (PMID 22179587, 2012). "miR-16 expression was studied by RT-qPCR in cancer cell lines with silenced PR, signal transducer and activator of transcription 3 (Stat3) or c-Myc, treated or not with progestins." (PMID 22583478, 2012). "Several previous studies have demonstrated that STAT3 is required for efficient cellular transformation by an array of well-characterized oncogenes including Ras, v-Src, SV40 T-antigen, and EGFR, further validating the importance of STAT3 in cancer biology." (PMID 22319590, 2012). "Although the STAT3 protein was first described as a member of the Jak/Stat signaling pathway, in some cancer cells STAT3 is also activated by non-Jak/Stat proteins, such as BCR-ABL, c-Abl, MEK1, Src and Smoothened." (PMID 23110199, 2012). "Notably, tyrosine-phosphorylated STAT3 has been found in up to 50% of late-stage NSCLC, suggesting a possible role in the etiology or progression of this cancer." (PMID 22319590, 2012). "Signal Transducer and Activator of Transcription 3 (STAT3), a common oncogenic mediator, is constitutively activated in many types of human cancers; therefore it is a major focus in the development of novel anti-cancer agents." (PMID 22754353, 2012). "It has been documented that STAT3 gene expression is regulated by mTOR signaling in cancer cells, however, it is not clear why the addition of clofarabine to temsirolimus resulted in further down-regulation of STAT3 gene." (PMID 23271044, 2012). "Subsequent comparison of selective epithelial, mesenchymal and cancer stem cell (CSC) markers between AD and NAD populations of CN and CR patients demonstrated an enhanced trend in mRNA expression of E-cadherin, EpCAM, STAT3 and Oct4 in the NAD population of CR patients." (PMID 23056490, 2012). "In these cancers, RET activates the ERK/MAPK, the PI3K/AKT/mTOR and the JAK/STAT3 pathways." (PMID 23056499, 2012). "In recent years, the effect of deletion of the chromosome 10 phosphatase and tensin homolog gene (PTEN), and expression of signal transducer and activator of transcription-3 (STAT3) and vascular endothelial growth factor-C (VEGF-C) have been investigated in malignant tumors." (PMID 23170117, 2012). "Cuc IIa is a novel class of anti-cancer drug in suppression of cancer cell expansion by disrupting the actin cytoskeleton and directing the cell to undergo PARP-mediated apoptosis through the inhibition of survivin downstream of JAK2/STAT3." (PMID 21304528, 2011). "Thus, besides YB-1, proteins such as Stat3 and Twist, hypoxia-inducible factor-α, and Slug have also been identified as markers of malignant progression and may be candidates for cancer biomarkers to be looked at in a future HNSCC biomarker screening programme." (PMID 22095225, 2011). "Therefore, actin cytoskeletal signaling is the common target of Cuc family's anti-cancer activity, which can converge on cell survival machinery through JAK2/STAT3-dependent and -independent mechanisms." (PMID 21304528, 2011). "Given that STAT3 is known to be activated in a wide spectrum of human tumors, another strategy to evaluate the potential of STAT inhibitors is to determine their activity on a large panel of highly annotated cancer cell lines." (PMID 21680956, 2011). "Thus, recently STAT3 and HIF-1α are attractive target molecules by natural compounds and herbal extracts in cancer research." (PMID 21731766, 2011). "Which signalling pathways are activated by CXCL1 through CXCR2 in dendritic cells is yet unknown, however studies in different cell types, such as cancer cells, show that CXCR2 signalling can activate NF-κB, STAT3 and the ERK pathways." (PMID 22125641, 2011).
cancer (continued). "We compared the gene expression profiles of samples expressing moderate/high levels of pStat3 within carcinoma cells to those with no activated Stat3 in either carcinoma cells, lymphocytes, stromal cells and endothelial cells." (PMID 22140473, 2011). "To find out whether IL-6 would be regulated by Stat3 in cancer cell lines other than AS2, we performed genetic siRNA experiments on two drug resistant cancer cell lines (KB-CPT100 and MCF-7/ADR)." (PMID 21122157, 2010). "We found that the NF-κB pathway was the most important, but not an essential, regulator of IL-6 secretion in the tested cancer samples and that Jak2/Stat3 pathway contributed substantially to the regulation of IL-6 secretion in many cancer samples." (PMID 21122157, 2010). "Therefore, Jak2/Stat3, MEK/Erk and PI3-K/Akt pathways individually contribute to the regulation of IL-6 autocrine production in cancer cells." (PMID 21122157, 2010). "Moreover, STAT3 expression and activation correlated well with HPV16 positivity in cervical precancer and cancer lesions which indicates its possible involvement in establishment of HPV infection and persistence." (PMID 20977777, 2010). "Furthermore, FLLL32 was found to be potent than other reported JAK2/STAT3 inhibitors, including FLLL32, WP1066, AG490, Stattic, S3I-201, and curcumin in our cancer cell lines." (PMID 20712901, 2010). "Analysis of 120 tissues from cervical precancer and cancer lesions or from normal cervix revealed differentially high levels of constitutively active STAT3 in cervical precancer and cancer lesions, whereas it was absent in normal controls." (PMID 20977777, 2010). "With the decreases of STAT3 phosphorylation and STAT3 downstream targets, the induction of apoptosis by FLLL32 was as evidenced by cleaved poly-ADP ribose polymerase (PARP) PARP and caspase-3 in these human cancer cell lines." (PMID 20712901, 2010). "Consistent with previous literature, we found that drug resistant cancer cells secreted more IL-6 secretion than the parental cells, and not only NF-κB, PI3-K/Akt and MEK/Erk but also Jak2/Stat3 pathway contributed to the autocrine production of IL-6 in these cells." (PMID 21122157, 2010). "STAT3 protein abundance was not affected at any IL11 concentration tested in all carcinoma cell lines." (PMID 20553623, 2010). "STAT-3 also regulates cellular functions such as cell proliferation, survival, differentiation as well as apoptosis, and dysregulation of the STAT system directly contributes to malignant transformation and cancer progression." (PMID 20030801, 2009). "Moreover, the activation of STAT3, an important transcription factor for regulating VEGF-A in cancer cells, was markedly reduced by ENMD-1198." (PMID 18651980, 2008). "Elevated Stat3 phosphorylation in these bladder tissues and cell lines might result from abnormal overactive upstream oncogenic FGFR or ERBB2 in these cancer tissues." (PMID 18939995, 2008). "In contrast, high levels of p-STAT3 (p = 0.01) and loss of PTEN (p = 0.01) appeared not to be associated with cancer progression." (PMID 18254976, 2008). "First, functioning as an inducible binding partner of an important transcription factor regulating many genes involved in tumorigenesis and cancer progression, HIF-1α is an end downstream effector molecule common to the ERK-, Akt-, and STAT3-mediated signal transduction pathways." (PMID 17931419, 2007). "In carcinoma cell lines, the major trends included a strong STAT3 activation by LIF (ADLC, H125), an increased (ADLC, H23) or decreased STAT3 activation by IL-6 (H125, H324), a decreased ERK activation by EGF (H522), and a treatment-independent, constitutive activation of the ERK pathway (H23)." (PMID 16271139, 2005).
cancer (continued). "The most prominent candidate on the role in the regulation of STAT3 phosphorylation by Sestrins that appeared in our search was the protein tyrosine phosphatase receptor delta (PTPRD), whose inhibitory effect on STAT3 phosphorylation in different cancer types was demonstrated in several studies." (PMID 39985075, 2025). "However, STAT3 was not one of the seven oncogenes identified as such targets in non-cancer cells in vivo." (PMID 40627772, 2025). "circHIPK3/miR-124-3p/miR-637/miR-338-3p are the most well documented interactions in various cancers types, and can control MAPK, Jak/STAT3, Wnt/β-catenin, and PI3K/Akt signaling pathways, and may be important for support the initiation and establishment of the cancer." (PMID 40061896, 2025). "have found that the JAK/STAT3 pathway could control the expression of several genes involved in lipid metabolism, such as carnitine palmitoyltransferase 1B (CPT1B) and fatty acid β-oxidation (FAO), to mediate cancer stemness and chemoresistance." (PMID 40052129, 2025). "Apigenin may exert its effects by interacting with various signaling pathways involved in cancer development, such as the PI3K/AKT/mTOR pathway, NF-κB, signal transducer and activator of transcription 3 (Stat3) pathways, angiogenesis, apoptosis, cell cycle, and inflammation." (PMID 41226811, 2025). "For cancer targets, isocaryophyllene showed the highest potential as a ligand in the binding domains of pyruvate dehydrogenase kinase 3 (PDK3) (PDB ID: 1Y8O) and signal transducer and activator of transcription 3 (STAT3) (PDB ID: 6NJS), with glide scores of −6.4 and −6.0 kcal/mol, respectively." (PMID 41226145, 2025). "With the different signaling pathways of resveratrol in cancers, resveratrol inhibits multiple intracellular mechanisms, such as β-catenin signaling, transforming growth factor (TGF)-β signaling, PI3K/Akt signaling, and Src/signal transducer and activator of transcription 3 (STAT3) signaling." (PMID 39857383, 2025). "Moreover, we observed an upregulation of other STAT3 target genes, including BCL-XL and BCL2, following olaparib treatment that was abrogated upon STAT3 silencing, supporting the concept that cancer cells via STAT3 hijack the upregulation of survival effectors, as BCL-XL and BCL2." (PMID 41350901, 2025). "STAT3, a cytoplasmic transcription factor belonging to the Janus kinase (JAK)-signal transducer and activator of transcription (STAT) signaling pathway, seeves as a pivotal regulator of tumorigenesis acting in cancer cells themselves and in immune cells and CAFs within the TME." (PMID 41280323, 2025). "Transcription factors such as STAT3 and NF-κB enhance IL11 transcription under inflammatory conditions, while cooperation with ERK signaling regulates processes including cell cycle progression, differentiation, and immune evasion in pathologies such as cancer and tissue injury." (PMID 41487426, 2025). "Importantly, pharmacological inhibition of STAT3 has demonstrated the ability to suppress OSCC growth and diminish cancer stem cell characteristics, underscoring its potential as a therapeutic target to improve treatment outcomes and overcome resistance mechanisms in OSCC." (PMID 40140827, 2025). "Furthermore, combined treatment with the EGFR/STAT3 inhibitor AG490 resulted in additional reduction of invasive cell numbers, demonstrating enhanced inhibitory effects on cancer cell migration and invasion when curcumin was administered in combination with AG490." (PMID 41312415, 2025). "However, decreased mRNA expression was observed for MLKL, STAT3, and HIF-1α in cancer cells." (PMID 41463386, 2025).